INS (insulin)
Diseases named in the same sentence as INS in open-access papers (continued):
Sharing a sentence is not in itself a finding about the gene and the disease.
Hypoglycemia (continued). "Thereis a risk of hypoglycemia around lunch time, the ratio of the insulin mixtureis manually changed in the morning to handle the condition." (PMID 18566688, 2008). "In a patient without previous treatment with insulin and sulfonylurea, failure to suppress endogenous insulin secretion in the presence of hypoglycemia is the hallmark of an insulinoma." (PMID 20108468, 2008). "Patients are more at risk of hypoglycaemia when the insulin sensitizer is combined with insulin or insulin secretagogues." (PMID 18215172, 2008). "In patients on lifestyle adjustment and/or insulin sensitizing treatments, the risk for hypoglycaemia is negligible." (PMID 18215172, 2008). "Because it is important that patients adhere to a strict meal schedule to minimize the risk of hypoglycemia, treatment with a premixed insulin regimen can limit patient flexibility with respect to mealtimes." (PMID 18279520, 2008). "The perceived risk of hypoglycaemia with insulin therapy has led to restrictions in licensing for driving." (PMID 18215172, 2008). "Laboratory tests showed the presence of hypoglycemia (30mg/dl) associated with an increased value of plasma insulin (16μU/ml)." (PMID 20108468, 2008). "Severe hypoglycaemia of 40 mg/dl or less was associated with the application of insulin in our setting, as well as in the cardiovascular surgical ICU study, but less frequent than in the medical ICU study." (PMID 18799004, 2008). "Sulfonylureas directly stimulate insulin secretion (ii above), but their glucose-independent action carries a risk for sometimes-fatal hypoglycemia." (PMID 18682834, 2008). "These are generally at least as effective in reducing HbA1c as conventional human insulin, and are associated with benefits including reductions in post-prandial plasma glucose, lower risk of hypoglycaemia and less weight gain." (PMID 18387078, 2008). "A recent meta-analysis in critically ill patients has demonstrated that intensive insulin therapy is associated with a sixfold increase in the relative risk of hypoglycemia and as much as 5.1 to 17.0% of patients develop glucose levels < 40 mg/dL." (PMID 19055829, 2008). "Clinical trials comparing insulin detemir and NPH insulin have indicated that treatment with insulin detemir results in comparable improvements in A1C, less weight gain, and reduced risk for hypoglycemia." (PMID 18279520, 2008). "In the diabetic pregnant the stress during the labour usually induces a further increase of blood glucose levels with a consequent rise of the fetal production of insulin and increased risk of hypoglycemia." (PMID 18593467, 2008). "Most of the research into hypoglycaemia has used insulin-induced hypoglycaemia as a tool and has looked at hypoglycaemia in the insulin-deficient Type 1 diabetic population." (PMID 18215172, 2008). "Hypoglycaemia of 60 mg/dl or less was also more frequently associated with the utilisation of insulin in the intensive group 66% compared with 10% in the conventional group." (PMID 18799004, 2008). "The concern regarding the risk of hypoglycemia with intensive insulin protocols has limited the expansion to general care areas." (PMID 17727725, 2007). "By contrast, the use of insulin secretagogues (sulphonylureas and glinides) is associated with an increased risk of hypoglycaemia." (PMID 17697384, 2007). "The most important risk associated with intensive insulin therapy is the occurrence of severe hypoglycemia." (PMID 17306016, 2007). "Thus, protein can be used in various ways to reduce the risk of nocturnal hypoglycemia, as well as hypoglycemia induced by physical activity, periods of fasting, and potentially even from excessive exogenous insulin administration." (PMID 41602572, 2026). "However, concerns about the risk of hypoglycaemia persist in individuals on a multiple daily insulin injections regimen." (PMID 41048193, 2026).
Hypoglycemia (continued). "Conditions associated with an increased risk of hypoglycaemia in these patients include reduced gluconeogenesis in the kidneys, inadequate nutrition, decreased insulin clearance, glucose loss in the dialysis fluid, and glucose diffusion into erythrocytes during HD." (PMID 41536569, 2026). "Improvement in blood acidosis may help manage early morning hypoglycemia associated with insulin antibodies." (PMID 42016496, 2026). "However, CGM-controlled systems raise new safety risks, as false CGMs readings can cause insulin overdose, which results in hypoglycemia and fatal consequences." (PMID 41524605, 2026). "Taken together, these results highlightedthat administration of oral casNP/insulin/C10 not onlyenhances insulin bioavailability and hepatic targeting but also offersa reduced risk of hypoglycemia by adapting insulin release in responseto the metabolic demand in diabetic mice." (PMID 41442621, 2026). "Women using insulin or other glucose-lowering agents need to be informed of the risk of hypoglycemia, as medication doses may require adjustments based on physical activity levels." (PMID 41008394, 2025). "However, insulin therapy was associated with a higher incidence of hypoglycemia (18% vs. 7%, p = 0.02) and weight gain (mean increase 2.3 ± 1.4 kg vs. 0.9 ± 0.8 kg, p < 0.001)." (PMID 40959330, 2025). "Hypoglycemia is the primary ADR associated with the continuous infusion of regular insulin owing to various factors such as excess insulin administration, hormonal deficiencies, concomitant medications, non-physiological conditions such as intubation, and variations in nutritional support." (PMID 40463907, 2025). "Caution to be exercised when prescribing SGLT2 inhibitors alongside insulin or insulin secretagogues, as this combination may increase the risk of hypoglycemia." (PMID 40235535, 2025). "Notably, drug-induced hypoglycemia commonly occurs with insulin and is a theoretical risk associated with other classes of β cell–regenerative drugs." (PMID 41031887, 2025). "AID systems with the ability to attenuate and suspend insulin for down-trending glucose could further mitigate hypoglycemia risk while driving." (PMID 40303943, 2025). "A percentage coefficient of variation (CV) threshold of 36% is often used to distinguish between stable and unstable glycemia, with higher variability being strongly associated with an increased risk of hypoglycemia, particularly in patients treated with insulin." (PMID 41301738, 2025). "In addition, the decreased risk of hypoglycemic events in the two-bag method holds significant value, given that in patients treated with insulin, hypoglycemia is associated with an increased risk of inpatient mortality and increased length of hospital stay." (PMID 41458864, 2025). "This may reduce their nocturnal risk of hypoglycemia and could be explained by the reduction in insulin secretion and sensitivity during aging." (PMID 40401234, 2025). "Increasing insulin doses might improve glycemic control, but it also, with unclear guidance of an effective dose, increases the risk of life‐threatening hypoglycemia." (PMID 41424588, 2025). "Studies evaluating interference from insulin analogs in automated immunoassays have produced varied outcomes, emphasizing the need to assess commercial assays comprehensively for improved diagnostic accuracy in hypoglycemia management." (PMID 39030378, 2025). "The mechanism(s) underlying the apparent increased male susceptibility to neonatal hypoglycemia may reflect fundamental sex differences in insulin sensitivity." (PMID 40373797, 2025). "Furthermore, children with AKI are at increased risk of hypoglycemia, as reduced kidney function prolongs the half-life of insulin which can result in vasodilatory effects with orthostatic change; however, this has not been clearly described in trials." (PMID 40272476, 2025).
Hypoglycemia (continued). "This high threshold may be due to concerns about hypoglycemia with insulin administration and associated morbidity, mortality, and long-term neurocognitive effects." (PMID 40272476, 2025). "An ultra‐long‐acting insulin (e.g., glargine 300 U/mL [Gla‐300]) with pre‐meal rapid‐acting insulin represents a valid alternative and is recommended for older people at risk of nocturnal hypoglycaemia or for frail individuals needing help from a carer or health professional to administer insulin." (PMID 39500566, 2025). "Reduced insulin sensitivity, impaired postprandial glucagon regulation, and declining hepatic and renal function may lead to inaccurate insulin dose recommendations, increasing the risk of cumulative hypoglycemia." (PMID 41180388, 2025). "Although the difference between groups was not statistically significant, this trend may reflect an increased risk of hypoglycemia when SGLT2 inhibitors are combined with insulin, as has also been reported in human medicine." (PMID 40796840, 2025). "The less‐than‐optimal glucose control, secondary to hypoglycaemia risk, drives the provision of insulin to the most physiologically available preparations, even where the gains with the latest analogues may be marginal." (PMID 40035222, 2025). "For instance, combining an SGLT2 inhibitor with insulin or sulfonylurea can enhance the risk of hypoglycemia, and adding an SGLT2 inhibitor to a loop or thiazide diuretic may exaggerate volume depletion and hypotensive effects." (PMID 41471118, 2025). "Even though insulin therapy (administered through multiple daily subcutaneous injections via insulin pens or through continuous subcutaneous infusion via insulin pumps) remains the mainstay of T1D management, it is associated with an increased risk of hypoglycemia and weight gain." (PMID 40004833, 2025). "Self-management of T1D in older adults presents unique challenges, including a high risk of hypoglycemia that must be mitigated in the setting of a lifelong requirement for insulin and evolving mismatches between intensive self-management demands and an older person's capacity for self-care." (PMID 41361045, 2025). "While sulfonylureas may increase the risk of hypoglycemia and mortality when combined with insulin, metformin enhances insulin sensitivity, and DPP-4 inhibitors have shown protective effects against stroke." (PMID 41011236, 2025). "Additionally, data do not distinguish between prandial versus basal insulin, and typically most hypoglycemia with insulin will occur in association with prandial insulin." (PMID 40245017, 2025). "Potential reasons for the association between female sex and neonatal hypoglycemia could be differences in hormonal and metabolic factors, insulin sensitivity, and differences in feeding patterns." (PMID 40953062, 2025). "Thus, the optimal treatment protocol (assuming glucose consumption is minimized) is to pick a safe target fasting glucose which avoids the risk of hypoglycemia, and then titrate the insulin dose to achieve this target glucose." (PMID 38895272, 2025). "Furthermore, acute hypoglycemia has been linked to reduced insulin secretion, suggesting a potential impairment of pancreatic function under such conditions." (PMID 41303503, 2025). "Insulin treatment prior to 36 weeks PMA was associated with longer time spent in hypoglycemia." (PMID 40576801, 2025). "Moreover, they cause hypoglycemia by increasing the circulating insulin amount, thus inducing insulin resistance." (PMID 41303162, 2025). "This study represents the first demonstration of a glucose‐responsive glucagon‐releasing microneedle patch for hypoglycemia prevention, highlighting its potential to reduce the risks associated with intensive insulin therapy and improve the quality of life for diabetic patients and their caregivers." (PMID 39887601, 2025).
Hypoglycemia (continued). "During hospitalisation, insulin requirements may fluctuate significantly, often resulting in a discharge insulin regimen that may be overly aggressive, thus increasing the risk of readmission and severe hypoglycaemia within the first 30 days after discharge." (PMID 40760249, 2025). "Despite these advances, the ultimate goal remains the development of insulin formulations that more closely mimic physiological insulin secretion, effectively controlling fasting and postprandial blood glucose levels while minimizing the risk of hypoglycemia." (PMID 40919135, 2025). "This heightened risk may be attributed to higher levels of PA potentially increasing insulin sensitivity and impacting the counterregulatory system, which could lead to inadequate insulin level control and an elevated risk of exercise-induced hypoglycemia." (PMID 38954647, 2025). "Alcohol consumption is another non-insulin mediated cause of hypoglycemia." (PMID 40648766, 2025). "Additionally, insulin users with T2D were assessed for hypoglycaemia risk on a regular basis, with at least 80% of survey participants reporting frequent assessments for recurrent hypoglycaemia (80.0%) or severe hypoglycaemia (88.6)." (PMID 39676327, 2025). "This may be because blood glucose control targets were more relaxed to avoid the risk of hypoglycemia after the publication of the 2017 guidelines in Japan, leading to a reduction in the dosage of SUs and insulin, while still being prescribed." (PMID 40777704, 2025). "As NPH insulin has the highest associated hypoglycemia risk of all investigated basal insulins, this could have contributed to an underestimation of the effect of switching to Gla-300." (PMID 40309264, 2025). "The pancreatic β-cell compensatory response to insulin resistance may cause hypoglycemia in TAIRS patients, although this is rare." (PMID 40565151, 2025). "The aim of this work is to develop a class of injectable biocompatible PBA-based copolymer microgels with tunable glucose-responsive thresholds for potential use in a self-regulated insulin delivery system at low risk of hypoglycemia using a simple and benign synthetic method." (PMID 40807234, 2025). "By considering the natural variation in insulin sensitivity throughout the day, clinicians can adjust insulin dosing regimens to more closely match the body’s metabolic needs, potentially reducing the risk of hypoglycemia and improving glycemic control." (PMID 40649840, 2025). "Some experts recommend them over regular insulin to reduce hypoglycemia risk." (PMID 40705102, 2025). "Patients with a history of nocturnal hypoglycemia might consider daytime administration to reduce this risk, along with use of second-generation basal insulin analogs like Gla-300, with lower hypoglycemia risk, especially nocturnal hypoglycaemia." (PMID 40190894, 2025). "Both MVPA and VPA are also associated with increased nocturnal hypoglycemia events, but the daily insulin dose may influence these relationships." (PMID 38954647, 2025). "However, the physiological changes that occur during pregnancy, including increased insulin resistance, significant blood sugar fluctuations, and a heightened risk of hypoglycemia, present considerable challenges to effective blood sugar control." (PMID 40997126, 2025). "Notably, the risk of severe or blood glucose-confirmed symptomatic hypoglycemia, adverse events, and severe adverse events was comparable between IDegLira and insulin degludec." (PMID 40958912, 2025). "In addition, insulin therapy, despite the fact that new analogs are developed, does not completely reflect the physiological action of endogenous insulin and still holds the risk of hypoglycemia episodes." (PMID 41373413, 2025). "From a clinical perspective, a reduction in insulin requirements is advantageous, as it may lower the risk of insulin-induced hypoglycemia and enhance owner compliance with treatment protocols." (PMID 40796840, 2025).
Hypoglycemia (continued). "Therefore, the aim of insulin therapy should be to improve glycemic control and improve quality of life, with a low risk of hypoglycemia (Grade 1C)." (PMID 41141497, 2025). "Additionally, metabolic changes during HD, including altered gluconeogenesis, reduced insulin clearance, glucose loss to the dialysate, and intracellular glucose diffusion, contribute to hypoglycemia but are difficult to monitor in routine clinical practice." (PMID 41293049, 2025). "Randomised controlled trials have consistently demonstrated that once‐weekly insulin efsitora alfa achieves HbA1c reductions comparable to those of daily insulin (glargine or degludec), while also reducing hypoglycemia risk, limiting dose adjustments, and simplifying titration." (PMID 41152194, 2025). "Insulin therapy is a critical component in the management of T2D, but it presents several challenges that can hinder its effectiveness, such as the burden of daily injections and the risk of hypoglycemia." (PMID 39810242, 2025). "In contrast, insulin usage demonstrated a significant association (OR = 1.590, CI: 1.100–2.290, p = 0.010) with hypoglycemia, highlighting that it is a key factor affecting the likelihood of hypoglycemia." (PMID 41393767, 2025). "However, failure to appropriately reduce the insulin dosage leads to an increased risk of hypoglycemia." (PMID 40828947, 2025). "Insulin overdose can cause severe, potentially fatal hypoglycemia." (PMID 41303503, 2025). "The daily insulin dose was almost halved (-21 units/day, p<0.001), which may also be associated with a lower risk of hypoglycemia and reduced insulin-related weight gain." (PMID 41268167, 2025). "However, in older adults, glycemic targets must be individualized to avoid hypoglycemia, especially with medications, including sulfonylureas (SUs), glinides (GLs), and insulin, which pose a high risk of hypoglycemia." (PMID 40777704, 2025). "These agents could offer an alternative or adjunct to traditional pharmacological treatments, such as insulin, which remains the gold standard but poses challenges due to its invasive administration and risk of hypoglycemia." (PMID 40076938, 2025). "However, insulin therapy is associated with various adverse effects, including severe hypoglycemia and ectopic fat accumulation, which can lead to atherosclerosis." (PMID 40429740, 2025). "However, the growing use of insulin analogs complicates diagnostic accuracy in cases of suspected factitious hypoglycemia." (PMID 39030378, 2025). "When blood glucose returns to the normal range, the activation efficiency of this signaling pathway decreases with the decline in blood glucose, and insulin secretion is correspondingly reduced, thereby reducing the clinical risk of hypoglycemia at the molecular mechanism level." (PMID 41573745, 2025). "-5 The first line of treatment of GDM is insulin, but its various disadvantages including parenteral application, i.e., need for multiple injections, risk of hypoglycemia, maternal weight gain, and higher cost decrease the compliance of the patients to the use of insulin." (PMID 41342237, 2025). "Additionally, having a low level of knowledge regarding insulin self-administration was significantly associated with a high prevalence of self-reported hypoglycemia." (PMID 40110390, 2025). "PTEN deficiency in the liver is associated with hypoglycemia and low insulin secretion." (PMID 40115165, 2025). "Some RCTs suggest metformin may reduce dementia risk, while insulin therapy in older adults may worsen cognition if hypoglycemia occurs." (PMID 41169480, 2025). "Insulin and sulfonylureas can likely cause hypoglycemia, a profound adverse effect that increases the risk of heart disease, may potentially lead to brain damage from repeated severe episodes, and can even result in death." (PMID 40507585, 2025). "In addition, exercise can not only improve insulin sensitivity and reduce the risk of hypoglycemia at night, but also lower systolic and diastolic blood pressure." (PMID 41250757, 2025).